IFNG (interferon gamma)
Diseases named in the same sentence as IFNG in open-access papers (continued):
Sharing a sentence is not in itself a finding about the gene and the disease.
sarcoidosis (135 papers, 2005 to 2026). Sarcoidosis is a multisystemic disorder of unknown cause characterized by the formation of immune granulomas in involved organs. "A hallmark of active sarcoidosis is the predominant expression of interferon-gamma in the affected organs, accompanied by the involvement of active cytokines, such as IL-2, IL-12, and tumor necrosis factor-alpha." (PMID 39598118, 2024). "In contrast to TB, sarcoidosis was associated with increased serum IFNγ levels and both IFN-I and II activity, as well as elevated serum IFNα2 in SU compared to those in TBU." (PMID 39309852, 2024). "As confirmation of our unbiased approach, we identified a number of immune modulators previously implicated in sarcoidosis, including IFNG, IL12, and IL17." (PMID 27460362, 2016). "Our correlation analysis revealed relationship of T-bet and sarcoid inflammation, namely, its association with key sarcoidosis-associated cytokine IFNG, and receptors IL2RB, IL15RA, CXCR3, and CXCR6, regardless of the disease outcome." (PMID 26696750, 2015). "The mechanisms of hypergammaglobulinemia in sarcoidosis are not fully understood, but three points seem to be clear: First, IFNg, a hallmark cytokine in sarcoidosis, is a potent stimulus of IgG secretion by B-cells." (PMID 26204953, 2015). "Both IFNγ and GM-CSF have been associated with sarcoidosis and disease activity." (PMID 33903979, 2021). "Sarcoidosis is characterised by a hyperactive T helper-1 (Th-1) immune response, prompting the release of interferon gamma (IFN-y) and other proinflammatory cytokines." (PMID 40689241, 2025). "Interferon gamma (IFNG) is the gene that encodes IFN-γ, a member of the type II interferon family and a key cytokine in sarcoidosis pathogenesis." (PMID 41463010, 2025). "There are theories regarding a link between sarcoidosis and cytokines, including Th1, IL-2, IL-6, IL-8, IL-12, IL-18, IL-27, interferon gamma, and tumor necrosis factor." (PMID 40259952, 2025). "In patients with sarcoidosis, elevated numbers of IFNγ-producing CD4+ T lymphocytes have been identified in bronchoalveolar lavage (BAL) fluid, peripheral blood, and mediastinal lymph nodes." (PMID 39309852, 2024). "Serum IFNγ concentrations were significantly (p < 0.001) higher in patients with sarcoidosis (median = 2.760 pg/mL) than in those with TB (median = 0.075 pg/mL) and HCs (median = 0.075 pg/mL)." (PMID 39309852, 2024). "Detectable levels of IFNγ in the serum of patients with sarcoidosis further underscores the involvement of IFNγ in this disease." (PMID 39309852, 2024). "Detectable levels of IFNγ were more frequently observed in patients with sarcoidosis (21/27:78 %) than patients with TB (5/22:23 %; p < 0.0001; Fisher's exact test) and HCs (2/32:6 %; p < 0.0001; Fisher's exact test)." (PMID 39309852, 2024). "The IFNγ signal has been reported to be increased in localized skin lesions of idiopathic sarcoidosis and Blau syndrome and IFNγ upregulates the expression of NOD2, acting as a priming signal, as previously reported." (PMID 35711422, 2022). "They revealed several biological processes related to the pathogenesis of sarcoidosis, such as cellular response to IL-1 and interferon gamma (IFN-γ), regulation of IL-6 production, and response to lipopolysaccharide." (PMID 35860586, 2022). "Cytokine production in sarcoidosis was initially featured by an increase in Th1 cytokines (IL-2, IL-6, IL-12, IL-18, TNFα, IFNγ), which is potentially responsible for the so-called classical (M1) macrophage activation." (PMID 32751786, 2020). "In sarcoidosis, the proinflammatory cytokines interferon gamma, tumour necrosis factor and interleukin-6 are released by monocyte-derived macrophages and lymphocytes in the lungs and other affected tissues." (PMID 27929051, 2016). "In sarcoidosis, the expressions of IFNγ and Tbx21 in CD4+ T-cells are up-regulated post-T-cell activation." (PMID 26254778, 2015).
sarcoidosis (continued). "Th1 cell accumulation in the lungs is characteristic of sarcoidosis and these cells spontaneously produce increased amounts of IL-2 and IFNγ in the BAL fluid." (PMID 25386143, 2014). "After BALF CD4+ lymphocytes were stimulated with ionomycin and phorbol 12-myristate acetate, there was an appreciable increase in secreted IFNγ but a decrease in IL-4 expression in sarcoidosis patients compared to controls." (PMID 26464848, 2013). "Sarcoidosis is characterized by marked elevation of T Helper 1 (Th1) genes such as interferon gamma (IFNγ) and IL-12." (PMID 24322444, 2013). "Cytokines like TNF-α, IL-12 and interferon gamma (IFN-γ) have been revealed to be involved in the formation of sarcoidosis." (PMID 23967151, 2013). "There is a report of exosomes from bronchoalveolar lavage fluid of patients with sarcoidosis inducing pro-inflammatory cytokine release (IFNG and IL-13) from PBMCs, but it is unclear as to what concentrations of exosomes were used." (PMID 22848702, 2012). "Furthermore, although SPP1-expressing macrophages were detectable in sarcoidosis, IFNG-expressing T cells were a more defining feature of sarcoidosis compared with NL and NXG." (PMID 39989459, 2025). "Interestingly, the genes upregulated in sarcoidosis macrophages were also enriched in the pathway “mTORC1 Signaling”, and “Interferon Gamma Response”." (PMID 38353578, 2024). "Furthermore, patients with TB had significantly (p < 0.0001) higher anti-IFNα2 and anti-IFNγ autoantibody levels than in patients with sarcoidosis; however, these concentrations were comparable to Indonesian HCs." (PMID 39309852, 2024). "Interestingly, 79 gene transcripts were upregulated both in sarcoidosis monocytes and macrophages, and these genes were enriched in “Interferon gamma” and “STAT3 Signaling” pathways, with the inclusion of both STAT3 and JAK3 gene transcripts." (PMID 38353578, 2024). "IFNγ serum concentrations were higher in sarcoidosis than that in TB patients (p < 0.0001)." (PMID 39309852, 2024). "Indeed, a distinct CD4+FOXP3- cluster present exclusively in the sarcoidosis samples, with a Th1 phenotype marked by upregulation of IFNG and to a lesser degree CSF2 (GM-CSF), was identified." (PMID 35668129, 2022). "IFNγ is a key mediator of granuloma formation in sarcoidosis." (PMID 32751786, 2020). "Interferon-gamma is a cytokine best known for its role in the activation of macrophages and the synthesis and maintenance of granulomas, which are the pathognomic findings of sarcoidosis." (PMID 33173621, 2020). "To further investigate the inflammatory capacity of patient exosomes with focus on innate responses, we added BALF exosomes from sarcoidosis patients or healthy individuals to allogeneic PBMCs and analysed the induction of IFNγ and IL-1β in different cell subsets." (PMID 32948789, 2020). "Compatible with this hypothesis we found an expansion of TFH1 cells within the BALF compared to sarcoidosis significantly correlating with the expansion of CD21low B cells, prone to provide both IFNγ and IL-21 co-stimulation." (PMID 33613543, 2020). "Additionally, in assessing the functional aspect of TLR-9, patients with sarcoidosis produced significantly less interferon-gamma upon stimulation with different stimuli." (PMID 33173621, 2020). "Exhaled breath condensate (EBC) offers a non-invasive approach to sampling the fluid lining the respiratory tract and our group has detected significantly elevated markers of macrophage activity (i.e. TNF-α, TGF-β1 and neopterin) and IFNγ in sarcoidosis EBC compared to healthy control subjects." (PMID 26254778, 2015). "Moreover, increased cytokine profiles have been verified by increased BALF IFNγ+/IL-4+ CD4+ T cell ratios in sarcoidosis patients." (PMID 26464848, 2013). "Moreover, blood NKT cells from sarcoidosis patients, when stimulated with a glycolipid stimulator, showed diminished levels of IFNγ, therefore suggesting that NKT cells exert regulatory activity which prevents disease progression." (PMID 26464848, 2013).
sarcoidosis (continued). "IFNγ plays a pivotal role in the immunopathogenesis of sarcoidosis." (PMID 26464848, 2013). "IFNγ is highly expressed in the BALF of sarcoidosis patients." (PMID 26464848, 2013). "In sarcoidosis, IFNγ production inhibits the expression of the immunosuppressive cytokine, IL-10." (PMID 26464848, 2013). "Based upon the literature, we developed a computational model of known interactions between essential immune cells (antigen-presenting macrophages, effector and regulatory T cells) and cytokine mediators (IL-2, TNFα, IFNγ) of granulomatous inflammation during sarcoidosis." (PMID 21637752, 2011). "It has been suggested that the induction or exacerbation of Sarcoidosis during IFNα therapy may be to IFNα stimulation of IFNγ secreting activated T-lymphocytes." (PMID 27713294, 2010). "In our study, serum IFNγ levels could discriminate between sarcoidosis and TB (Youden's index = 0.64, sensitivity = 78 %, specificity = 86 %, and AUC = 0.785) as well as between SU and TBU (Youden's index = 0.61, sensitivity = 69 %, specificity = 92 %, and AUC = 0.769)." (PMID 39309852, 2024). "The inflammatory response in sarcoidosis is characterized by the increased production of several inflammatory cytokines produced by type 1 helper T (Th1) cells and macrophages, such as interleukin-2 (IL-2), interferon-gamma (IFN-γ), and tumor necrosis factor alpha (TNF-α)." (PMID 22393278, 2012). "PSMB9, a gene downstream of STAT1, which is known to integrate with IFNG and to play a proteolytic role in MHC1 antigen presentation, has been reported to be upregulated in sarcoidosis." (PMID 36203777, 2022). "Similary, it has been shown that sarcoidosis blood monocytes react to TB antigens including, ESAT6 and KatG with increased interferon gamma production." (PMID 35048206, 2022). "Recent sarcoidosis studies also implicate Th17.1 cells, a novel T cell subset expressing CCR6 but producing IFNγ." (PMID 32405439, 2020). "AMs are also the main source, together with lung T cells, of interferon gamma (IFNγ), which is highly expressed in the BALF (Bronchoal Veolar Lavage Fluid) of sarcoidosis patients." (PMID 32722050, 2020). "We previously found that BALF exosomes from sarcoidosis patients are enriched in CD54 and MHC molecules and induce IFNγ in autologous PBMCs, presumably contributing to inflammation." (PMID 32948789, 2020). "The close relationships in sarcoidosis as a whole were found between T-bet and IL2RB, IL15RA, and CXCR3, which was related to CXCR6 and IFNG." (PMID 26696750, 2015). "A cross-sectional study was conducted to investigate the expression of TH1 cytokines and transcription factors (IFNγ, IL-27 and T-bet) in the peripheral blood and/or EBC of sarcoidosis patients and healthy controls." (PMID 26254778, 2015). "This analysis further supported the crucial relationships between T-bet, CCL5, IFNG, IL2RB, and IL15RA, together with let-7d and miR-202 in progressing sarcoidosis." (PMID 26696750, 2015). "In regressing sarcoidosis, relationships were observed between T-bet and IL2RB, IL15RA, CXCR3, IL2, and IFNG." (PMID 26696750, 2015). "Under unstimulated conditions, the difference in the percentages of IL-4 and IFNγ secreting CD4+ lymphocytes in BALF and peripheral blood of sarcoidosis patients is insignificant." (PMID 26464848, 2013). "It has also been shown that upon stimulation, compared with controls, there are increased numbers of CD4+IFNγ+ cells in both BALF and induced sputum of patients with sarcoidosis." (PMID 26464848, 2013). "Of the 31 TCR/JS/CCR-gene signature genes, 8/31 genes were cited in the sarcoidosis literature with CD28, IFNG, IL7R, AKT3, IL2RA, IL2RB, and STAT4 demonstrating a robust relationship with these terms." (PMID 22984568, 2012). "The pathophysiology of sarcoidosis involves activation of macrophages and CD4+ T lymphocytes, leading to increased production of tumor necrosis factor-alpha (TNF-α), interleukin-2 (IL-2), interferon-gamma (IFN-γ), and serum amyloid A protein." (PMID 40988789, 2025).
sarcoidosis (continued). "The upregulation of IFNG and IFNLR1 may be related to EPL development and could serve as potential therapeutic targets for sarcoidosis." (PMID 41463010, 2025). "However, the most striking feature of sarcoidosis lesional T cells was their very strong and significant upregulation of STAT1 and IFNG." (PMID 39989459, 2025). "By contrast, T cells from sarcoidosis patients exhibited clonal expansion of terminally differentiated CD8+ effectors that expressed high levels of effector genes, including CCL5, GZMB, PRF1, IFNG, KLRG1 and ZEB2." (PMID 40469525, 2025). "Two studies described identical IFNγ serum concentrations in TB and sarcoidosis, but this was not explored in relation to uveitis." (PMID 39309852, 2024). "Observed levels of anti-IFNα2 autoantibodies in HCs, sarcoidosis, and TB were substantially lower compared to the level of anti-IFNα2 observed in a patient with APECED (MFI = 29380) and anti-IFNγ in a patient with AOID (MFI = 33381) as detected at a 1000-fold serum dilution." (PMID 39309852, 2024). "Several theories exist as to why etanercept causes intraocular inflammation, contrary to its TNF α counterparts, it does not inhibit interferon gamma (IFN-γ) which has been shown to cause intraocular inflammation, scleritis, and a sarcoidosis-like syndrome." (PMID 37589912, 2023). "We found significant expression of IFNG in lymphocytes in the sarcoidosis cases, but not normal lung or skin." (PMID 35668129, 2022). "There were no statistical differences in PBMC IFNγ mRNA levels between controls and sarcoidosis patients (p = 0.68)." (PMID 26254778, 2015). "In progressing sarcoidosis, T-bet related to CCL5, IL2RB, IL15RA, and IFNG." (PMID 26696750, 2015). "Furthermore, the positive T-Spot result strongly supported TB infection, as interferon-gamma release assays do not typically yield positive results in sarcoidosis." (PMID 41195406, 2025). "Besides IFNγ, a recent meta-analysis conducted on gene-expression studies from several different tissues revealed that type I IFN mediated signaling pathways are also prominently involved in sarcoidosis." (PMID 39309852, 2024). "Pathway analysis was performed and indeed IFN-γ was the most highly significant predicted upstream cytokine regulator of Mac SAR-1 clusters based on their transcriptional profile and consistent with the upregulation of IFNG observed in CD4+ T cells in sarcoidosis." (PMID 35668129, 2022). "IFNγ and IL-10 were not significantly different between sarcoidosis patients and healthy controls." (PMID 27929051, 2016). "Mirroring mRNA data and data from another study that analysed intracellular IFNγ protein expression using flow cytometry, IFNγ protein levels were not elevated in PBMCs of sarcoidosis patients, suggesting that mechanisms within PBMCs may be implicated for the suppression of IFNγ." (PMID 26254778, 2015). "Therefore, we used highly-sensitive immunoassays and bioassays to measure IFNα2, IFNγ, IFN activity, and IFN-autoantibodies in serum from patients with active TB and sarcoidosis, with and without uveitis, and additionally explored potential diagnostic utility." (PMID 39309852, 2024).
type 1 diabetes (132 papers, 2006 to 2026). "IFNγ and IL1β are implicated in late, adaptive immune processes in islets in type 1 diabetes." (PMID 38081640, 2024). "To investigate whether DSG2 supports islet survival, we challenged isolated islets with the cocktail of pro-inflammatory cytokines implicated in the development of type 1 diabetes; namely TNFα, IL-1β, and IFNγ." (PMID 36309486, 2022). "Of special interest to immunoproteasome activation in β-cells are the effects of IFNβ, a type I IFN secreted by virus-infected cells and implicated in type I diabetes onset, compared to IFNγ, the classic immunoproteasome inducer secreted by cells of the immune system." (PMID 23383295, 2013). "Interestingly, loss of IFNγ-producing MAIT cells has recently been reported in type 1 diabetes." (PMID 29868028, 2018). "We observed reduced CXCR3 expression on antigen-experienced B cells in individuals with a long duration of type 1 diabetes, although B cells remained responsive to IFNγ." (PMID 41273416, 2026). "Such activation was increased when cells were stimulated with IFNγ alone in donors with type 1 diabetes, and this was evident in both DN and SWM B cells in both RO and LD individuals." (PMID 41273416, 2026). "In patients with type 1 diabetes, Nets enhanced DCs maturation and inflammatory cytokine production, thereby promoting a proinflammatory state and IFNγ-producing T lymphocytes." (PMID 41196933, 2025). "Monoclonal cell populations were treated with pro-inflammatory cytokines (IL-1β, IFNγ, and TNFα) to model type 1 diabetes (T1D) in vitro." (PMID 38562689, 2024). "In type 1 diabetes, most studies have focused predominantly on the release of the cytokines IL-1β, TNFα and IFNγ, and their role in beta cell damage." (PMID 37762318, 2023). "The cytokines interleukin-1β (IL-1β), interferon-γ (IFNγ) and tumor necrosis factor-α (TNFα) are the main mediators of beta-cell death and are commonly used in vitro as a model of type 1 diabetes pathogenesis." (PMID 37113489, 2023). "Interferon-gamma (IFN-γ), TNF-α, and IL-1β are closely associated with the development of type I diabetes." (PMID 36386181, 2022). "Expression of IFNB (p = 4.00 × 10−2, 95% CI −0.30, −0.006) and IFNG (p = 2.30 × 10−3, 95% CI −0.32, −0.06) was increased by 58% and 65%, respectively, in new-onset type 1 diabetes." (PMID 33973017, 2021). "An increase in H3K9ac levels at the same promoter regions of HLA-DQB1, which was hyperacetylated in type I diabetes patients was found after Interferon gamma (IFNγ) and TNFα stimulation." (PMID 33401659, 2021). "In mouse models of type I diabetes, as well as in type I diabetic patients, exFoxp3 or Foxp3 expressing cells produce IFNγ 9,11." (PMID 29545616, 2018). "In conclusion, intrinsic mitochondrial dysfunction observed in type 1 diabetes alters mitochondrial ATP and IFNγ production; the latter is correlated with ROS generation." (PMID 28883439, 2017). "The TH1 lineage, characterized by high levels of IFNγ production, is considered an important component of type 1 diabetes pathogenesis." (PMID 28883439, 2017). "We sought to understand whether B cells from individuals with type 1 diabetes also show an overall reduction in response to IFNγ, an inflammatory cytokine that upregulates CXCR3 expression." (PMID 41273416, 2026). "Further studies aimed at defining the pathophysiological role of IFNγ in type 1 diabetes are warranted and may identify rational points of intervention to halt beta-cell killing." (PMID 37113489, 2023). "We presently used a 7-stage protocol to generate beta cells from human iPSC and evaluated whether these cells are responsive to the pro-inflammatory cytokines (IFNγ, IL-1β, or IFNα) that play a role in type 1 diabetes." (PMID 31900242, 2020). "Moreover, the production of interferon gamma of NK cells promotes the auto-aggressiveness of T cells in patients with Type I diabetes and modifies the immune defense towards an excessive, uncontrolled, and unresolved response." (PMID 33371393, 2020).